AR (androgen receptor)
Diseases named in the same sentence as AR in open-access papers (continued):
Sharing a sentence is not in itself a finding about the gene and the disease.
cancer (continued). "However, over time, some cancer cells are able to survive and grow during this therapy, resulting in an androgen-independent type because of the reactivation and abnormal activation of the androgen receptor (AR)." (PMID 35053570, 2022). "However, stronger inhibition of AR signaling also leads to cancer cell resistance to antiandrogens." (PMID 36050295, 2022). "However, apart from those “AR-dependent” castration-resistant adenocarcinomas, a subset of patients has been found to progress with AR-independent cancer biology with a short-term response to hormonal treatment, early and extensive visceral metastases and poor outcomes." (PMID 35109899, 2022). "Except for these targets, the following proteins related to cancer cell proliferation could also be targeted by PROATCs: AR, ALK, BLK, BRD7/9, CDK2/5, CDK8, CDK9, Cdc20, c-Met, CREPT, CYP1B1, DHODH, ER, ERK1/2, FLT-3, HER2, MEK1/2, KRASG12C, GSPT1, PLK1, SLC9A1, TACC3, TRIM24, TRKA/C, Wee1, α1A-AR." (PMID 35410300, 2022). "However, in human cancers, including PC, non-nuclear AR signaling has been associated with aggressive characteristics, including epithelial-mesenchymal transition and metastasis." (PMID 35163087, 2022). "Therefore, ER or AR combines with SETD7 might serve as the panel of prognostic markers or therapeutic targets for patients with such cancers." (PMID 35812730, 2022). "Indeed, we found that the expression of AR significantly increased in type I cancers." (PMID 35814433, 2022). "In one patient, we detected increased copy numbers of both MYM and AR indicating major Chr X amplification (CN of Chr X: 4.30), also indicating possibly heterogeneous Chr X amplifications considering that cfDNA is a pool DNA released by cancer and normal cells." (PMID 35011998, 2022). "In addition, the ligand activated transcription factors and hormone receptors estrogen receptor (ER) and androgen receptor (AR) can indirectly change miR abundance through several signaling pathways but also activate the transcription of certain miRs in cancer." (PMID 33672261, 2021). "Actually, the most likely scenario is that AR activation or blockade could serve as adjunctive therapy in chemotherapeutic and immunotherapeutic (even chemoradiation/radiotherapeutic) approaches to combat a wide variety of cancers." (PMID 34831054, 2021). "Indeed, given such widespread expression of the target (AR) molecule, it might be questioned whether androgen receptor inhibition would today be licensed de novo for use in any but the most terminally ill cancer patients!" (PMID 33477370, 2021). "Thus, in the therapy of these cancers, the ER and the AR are targeted by antagonist compounds." (PMID 34137734, 2021). "We retrospectively analyzed the mRNA expression of AR using RT-qPCR in 95 patients with high-risk NMIBC treated with a bladder-sparing approach and correlated AR with clinical data and recurrence-free survival (RFS), cancer-specific survival (CSS), and overall survival (OS)." (PMID 34209360, 2021). "However, knowledge from PC on the class C-VI of TRIM proteins and their interaction with AR might be translatable and useful in ERα-driven cancer types." (PMID 34208621, 2021). "The coadministration of TPA and EGCG in cancer model systems might be a promising approach to promote both the synergic inhibition of AR signalling mediated by the LMTK2 inhibitory action and the down regulation of PI3K-Akt-mTOR pathway directly by means of EGCG." (PMID 34064250, 2021). "CRPC is defined as cancer that continues to proliferate in the absence or depletion of testosterone, compared to early stages that require higher levels of testosterone for survival and formation, but AR signaling remains an essential contributor to PCa progression." (PMID 35372800, 2021). "Thus, HSP90 inhibition may affect the stability of other oncogenic HSP90 clients in addition to AR-FL/AR-V7 in cancer cells." (PMID 33391515, 2021).
cancer (continued). "The AR gene has subsequently been experimentally deleted in this cell population, after which the ability of the mice to form tumors was only somewhat compromised, and small populations of cancer cells with NE differentiation developed, similar to those seen in a proportion of patients." (PMID 33477370, 2021). "From a therapeutic point of view, it is evident that in cancers in which Ado acts as a foe, the use of antagonists of ARs may help, and this is the basis of trials to assess the efficacy of AR antagonists as boosters of chemotherapeutic agents, with potential also in radiotherapy." (PMID 34831054, 2021). "In this review we discuss the role of the androgen receptor in PCa and how the combination of structural information and functional screenings is continuing to be used for the discovery of new drug to switch off the receptor or modify its function in cancer cells." (PMID 33572755, 2021). "Interestingly targeted inhibition of the downstream effector Hsp27 blocks this feed‐forward loop that restores AR signaling and could therefore be exploited to enhance anti‐cancer activity of ARPI." (PMID 33709547, 2021). "Moreover, the AR’s value as a drug target is strengthened by the concept that the molecular apocrine BCa and castration-resistant PCa (CRPC) cells share a core AR cistrome and target gene signature linked to cancer cell growth." (PMID 34137734, 2021). "KLKs, the largest secreted serine protease family, are involved in cancer cell growth, migration, invasion, and chemo-resistance by activation of PARs, the release of active growth factors, modulation of the proteolytic network, and activation of androgen receptor signaling." (PMID 33597040, 2021). "AR provides an ideal model to study TF-mediated mutations as this nuclear receptor is critical to the growth of nearly all PCa tumors, but is not active or required in other cancers." (PMID 32047165, 2020). "Furthermore, our present study showed that its overexpression could confer in vitro resistance to androgen-deprivation and antiandrogen, and also in vivo castration-resistant growth capacity of AR-positive cancer cells." (PMID 32226548, 2020). "Therefore, Vav3 overexpression may contribute to androgen receptor (AR) signaling through the PI3K-Akt pathway to stimulate cancer cell growth." (PMID 32322580, 2020). "In addition to ER and AR, other NRs can regulate miRNA expression in cancer." (PMID 32138313, 2020). "Thus, it is not suitable to use PC3 or DU145 cells to study whether SIRT7 affects cancer cell proliferation and invasion by influencing the AR signaling pathway." (PMID 32019578, 2020). "Importantly, an increase in ARBS mutations was not seen in those cancers that do not express or require AR." (PMID 32047165, 2020). "Thus, several AR-positive PCa cell lines demonstrated increased dependency on GPX4 activity in response to ATTs, a characteristic previously shown to be associated with drug-induced persister cells in other types of cancer in response to different therapies." (PMID 32577235, 2020). "Thus, the AR is also an important drug target for these aggressive AR positive cancers." (PMID 32650419, 2020). "Moreover, recent data suggest that AR-targeted therapies may enhance chemotherapy efficacy even in TNBC with low AR expression by targeting cancer stem cell-like cells." (PMID 32429078, 2020). "As androgen receptor antagonists that prevent androgen–AR interaction, flutamide and bicalutamide have been used for years, and recently more potent AR antagonists, such as enzalutamide, has been applied to CRPC and reported to decrease the risk of cancer progression and death." (PMID 32106418, 2020). "Descriptions of the difference in AR behavior in benign and PC cells go back nearly two decades to pioneering work from Gao and Isaacs, who demonstrated ‘that during transformation of androgen‐responsive normal prostatic epithelial to malignant cancer cells, a shift in the AR axis occurs’." (PMID 31520575, 2019).
cancer (continued). "However, whether AR expression modifies the efficacy of selective ER modulators or aromatase inhibitors for ER+ cancers remains unclear." (PMID 30795773, 2019). "Similarly, as estrogen targets platinum to the cancer cells displaying ER receptors, testosterone could target platinum to cancer cells displaying androgen receptor (AR) in order to increase deoxyribonucleic acid (DNA) and enhance the anticancer activity." (PMID 31582964, 2019). "AR could inhibit the proliferation and survival of cancer cells by up-regulating PTEN directly." (PMID 31905767, 2019). "Resistance of cancer cells to the various treatments being used involves complex cellular processes; these include the induction of anti-apoptotic genes, adapting new signaling pathways, genetic instability coupled to clonal selection, and ligand-independent androgen receptor (AR) transactivation." (PMID 31426412, 2019). "Therefore, the data indicate that the paclitaxel → AR/AhR → ABCG2 axis might form a positive feedback regulatory loop for cancer to develop chemoresistance." (PMID 30986993, 2019). "The observation that miR-361-3p produces a greater increase in region 1 and 7 AR 3′UTR activity in C42 cells as compared to HEK293T cells (Fig. 2dii, vi) may reflect the increased importance of this mode of AR regulation in AR-requiring PC cells as compared to non-cancer lines." (PMID 31043708, 2019). "However, AR positive cancers appear to rely more predominantly on HOXB13 for proliferation." (PMID 31273254, 2019). "Indeed, the role of FOXA1/AR co-expression in ER+ BC has not been investigated, although it has been suggested that the relative ratio among FOXA1, ER and AR could influence growth and aggressiveness of cancer cells." (PMID 29970021, 2018). "Nevertheless, we hypothesize that AR signaling in PCa cells uses CaMKK2 as a downstream hub regulating several molecular mechanisms in OBs, OCs, and macrophages to manipulate the BM niche to the benefit of the cancer cells." (PMID 29967592, 2018). "Thus, the PShTert-AR myofibroblasts, in an androgen depleted environment, could control all cancer cell lines tested, whilst the PShTert myofibroblasts could not and were themselves destroyed." (PMID 29721186, 2018). "Thus, AR might regulate the Nanog pathway to promote the stem-like differentiation, proliferation and migration of some cancer cell types." (PMID 29716628, 2018). "Additionally, AR may stimulate cancer development and progression possibly by expanding the population of cancer stem cells (CSCs)." (PMID 29716628, 2018). "Moreover, mounting experimental and clinical evidence have also suggested a central role for the signaling networks operating to promote a metastatic and/or therapeutic resistance cascade in cancer development that involves interactions of AR, TMPRSS2, HGF and c-MET with critical components of TMEs." (PMID 29587825, 2018). "Furthermore, we investigated whether selinexor could potentiate the anti-cancer activity of new anti-AR agents (enzalutamide and abiraterone) through the downregulation of AR and ARv." (PMID 30450161, 2018). "Moreover, IL-6 could have a crucial role in the activation of androgen receptor (AR) in cancer cells." (PMID 28389628, 2017). "The AR itself may be a primary target of therapy of enzalutamide-resistant cancers." (PMID 29214142, 2017). "Furthermore, AR, one target gene of hsa-miR-3148, was enriched in pathways involved in cancer." (PMID 28904974, 2017).
cancer (continued). "As AR controls a transcriptional program in normal prostate, which could cloud the assessment of cancer specificity of the gene sets studied, GSEA was done also using gene expression profiles from CaP and normal bone marrow, the most common site of metastatic CaP seeding." (PMID 28826481, 2017). "AR expression loss could be due to outgrowth of an AR negative cell present in the primary cancer, or loss of AR expression during cell culture in androgen-depleted medium." (PMID 28103576, 2017). "It is well-known that the expression of AR may critically influence cancer progression." (PMID 29214142, 2017). "Our results reinforce previous studies that AR-targeted therapy maybe insufficient to achieve long term PCa responses in some patients and show that co-targeting the AR axis and fat oxidation may provide additional anti-cancer benefit." (PMID 28915573, 2017). "Importantly, the present study shows that patients affected by tumors with increased AR expression have a favorable clinical course with a 5-year cancer-specific survival rate of 80% in ccRCC patients (90% papRCC) compared to 67% affected by ccRCCs with low AR expression (69% papRCC)." (PMID 29108248, 2017). "Alternatively, overexpression of AR may act as an oncogenic event in some carcinomas ex-PA." (PMID 28208703, 2017). "The discovery of a chaperone function of CHKA for AR signaling might also have wider implications in the treatment of other cancers and should accelerate the screening of potential CHKA inhibitors that will not only inhibit the catalytic function but also decrease the CHKA protein level." (PMID 26657335, 2016). "In this study, we found that AR expression was associated with a reduction in primary tumor CD90+ populations, a reduction in cancer cell migration, and an increase in CTC death, indicating that increased expression of AR might protect against postoperative HCC recurrence." (PMID 27340775, 2016). "Therefore, the suggested 3D cryogel scaffold could be the basis for developing a tunable cell culture platform for cancer research and screening for anticancer drugs, especially anti-AR drugs." (PMID 27386348, 2016). "Furthermore, pathway-based analysis of intergenic hydroxymethylation revealed extensive differential functional enrichment between normal and cancer cell lines, suggesting a putative role for intergenic 5hmC in the aberrant upregulation of proliferation androgen receptor signaling in cancer." (PMID 26981160, 2016). "However, contrary views were raised pointing out the failure to reproduce physical interactions between these lncRNAs and AR, the lack of an association of these lncRNAs with poor disease outcomes, and unchanged levels of these lncRNAs in metastasized cancer." (PMID 26690121, 2015). "Therefore, further knowledge of key regulatory ncRNAs involved in the simultaneous targeting of many pathways, such as the AR signaling axis and cancer metabolic reprogramming, will provide new insights into the development of precise and efficacious anti-CRPC therapies." (PMID 26690121, 2015). "Several mechanisms that may lead to tumor recurrence/metastasis have been proposed, including the amplification or mutation of androgen receptor, expression of multidrug resistance gene, epithelial-mesenchymal transition (EMT) and cancer stem cells (CSCs) or cancer stem cell-like cells." (PMID 25237769, 2014). "This suggested that CDK11p58 might inhibit the cancer cell migration through AR signaling." (PMID 24397471, 2014). "Indeed, AR mediates EGF proliferative activity in various cancer cells." (PMID 24130806, 2013).
cancer (continued). "Among these increased cytokines by AR silencing, CCL2 has drawn our attention since early studies have shown CCL2 could promote cancer metastasis via recruitment of macrophages and the molecular mechanism of AR silencing-induced CCL2 expression remains elusive." (PMID 23982944, 2013). "Besides using a different patient population, the major difference between our work and theirs is that they only considered cancers that were “strongly positive” for DEK expression; here, we uncovered an association between ER/PR/AR positivity with any degree of DEK staining." (PMID 23071688, 2012). "The model of Eikenberry and coworkers focuses on the potential to describe the evolution of cells under varied androgen exposures that might result in transitions to cancer and altered regulation of androgen receptor levels impacting the success or failure of antiandrogen oncology treatments." (PMID 22970204, 2012). "But considering that there was no preceding administration of flutamide and shortness of the duration of flutamide prescription, it was not very probable that there existed mutations in androgen receptor which would drive cancer growth as flutamide binds to the receptor as an agonistic ligand." (PMID 21754927, 2012). "Our finding that elevated testosterone levels were associated with AR-absent expression in ER-negative tumors identified a particular subset of cancers whose growth may be stimulated by androgens." (PMID 23241075, 2012). "However, recent evidence has shown that cancer progression at this stage is, again, often mediated by AR signaling, so that subsequent AR targeting may further contribute to disease control and, eventually, survival improvement." (PMID 24970135, 2012). "Hence, the Pax6-mediated repression of AR activity may be important and relevant in certain tissues, and also in specific cancer cells aberrantly expressing both proteins." (PMID 21935435, 2011). "The observation of deregulated AR expression in the cancerous lesions found in Men1 mutant mice suggests that menin inactivation and subsequent AR deregulation in these cells may lead to the disturbance of the AR pathway, which could in turn promote the progression to cancer." (PMID 20663219, 2010). "However, low intraprostatic androgen, whether induced by low serum T or 5α-reductase inhibition, can increase selection for AR overexpression, and hence increased cancer aggressiveness and treatment resistance." (PMID 20406442, 2010). "Another striking effect of clorgyline was the induction of androgen receptor (AR) and classic AR target genes such as prostate-specific antigen together with other secretory epithelial cell-specific genes, suggesting that clorgyline promotes differentiation of cancer cells." (PMID 19691856, 2009). "Our DSP analysis further supports this idea by revealing that AR protein expression negatively correlates with CD45 abundance in ovarian and SARC cancers, and with CD4 in SARC, reinforcing AR’s role in promoting an immunosuppressive TME." (PMID 41486951, 2026). "In most cancers, except DLBC and Thymoma, robust and significant inverse relationships concordantly existed between AR activity and the prognostic immune signatures." (PMID 41486951, 2026). "All participants had prior cancer-related therapy including ADP and an androgen receptor-targeted therapy or chemotherapy." (PMID 41493473, 2026). "Notably, our findings suggested that low AR activity may reflect higher immune infiltrates and IFNγ immune signature activity in the TME, which is also associated with improved response to ICB treatment in various cancers." (PMID 41486951, 2026). "More recent studies indicate that the GPX4‐mediated antiferroptosis effect can be suppressed by tripartite motif 36 (TRIM36), low‐dose antimony treatment, or AR inhibition, which reverses the NET process and has demonstrated effectiveness in treating cancers." (PMID 40900810, 2025).